BRAF (B-Raf proto-oncogene, serine/threonine kinase)
Diseases named in the same sentence as BRAF in open-access papers (continued):
Sharing a sentence is not in itself a finding about the gene and the disease.
melanoma (continued). "The TCGA network (The Cancer Genome Atlas Network) has now established a classification of cutaneous tumors according to their mutational status for genes BRAF, NRAS and NF1, all known as major actors of tumor initiation for melanoma." (PMID 29081790, 2017). "Based on these resistance mechanisms, combination of BRAF and MEK1/2 inhibitors (such as Vemurafenib plus Trametinib) is applied for BRAF mutant melanoma." (PMID 28387310, 2017). "While checkpoint blocking antibodies have been independently effective at increasing survival of subsets of patients with melanoma, combining immunotherapies with BRAF and MEK inhibitors is an enticing prospect." (PMID 29100459, 2017). "While previously published studies have defined a role for Cdc42 in regulating melanoma cell movement, this study represents the first identification of a specific Cdc42 signaling network that cooperates with BRAF to regulate melanocyte growth in vivo." (PMID 28753606, 2017). "Most studies on the resistance mechanisms and the reversible adaptive response of melanoma cells to BRAF inhibition have been conducted on cell lines artificially homogenized for these resistance traits through chronic vemurafenib exposure." (PMID 28573821, 2017). "This proportion is higher than commonly quoted in the literature, where BRAF mutant-positive melanomas are reported to comprise around 40% of the total melanoma population." (PMID 28819707, 2017). "We found LKB1 inactivation cooperate with BRAF V600E lead to melanoma cells more aggressive by a series of experiments including wound scratch test, Transwell assay." (PMID 29371951, 2017). "Recently, some therapies targeted against BRAF mutations (Vemurafenib, Dabrafenib), KIT mutations (Imatinib) and inhibitor of MEK1 and MEK2 (Trametinib) showed good results in advanced stage melanoma." (PMID 29069859, 2017). "To further understand the effect of BRAF/MEK inhibition on the interaction between melanoma cells and the immune system, we have examined the potential effect of BRAF/MEK inhibitors on the expression of CD47 in melanoma cells." (PMID 29050218, 2017). "We reported that in BRAF-mutant melanoma cells, PMCA4b expression is specifically upregulated by the inhibition of the Ras–Raf–ERK pathway with BRAF or MEK inhibitors." (PMID 28596940, 2017). "Another important finding of this study is that NRF-1 is responsible for ERK-mediated constitutive expression of CD47 and its upregulation upon BRAF/MEK inhibitor treatment in melanoma cells." (PMID 29050218, 2017). "In the BRAF Inhibitor in Melanoma 3 (BRIM-3) study, vemurafenib was more effective in BRAFV600E mutated melanoma compared to conventional chemotherapy (dacarbazine and DTIC)." (PMID 28350340, 2017). "First, CK2α overexpression in BRAF-mutant melanoma cells decreased sensitivity to BRAF inhibitors (vemurafenib, dabrafenib) and MEK inhibitor (trametinib)." (PMID 28134850, 2017). "A 54-year-old male with conjunctival BRAF wild-type melanoma metastatic to bilateral lungs and cervical lymph nodes received nivolumab and ipilimumab combination in an expanded-access program." (PMID 29900017, 2017). "In the wake of recent publications investigating the role of the BRAF oncogene on metabolic processes, we wanted to explore the effects of BRAF inhibitors on melanoma cells." (PMID 28595656, 2017). "Treatment of SKMEL28 human melanoma cells with the Hsp90 inhibitor 17-AAG (50 nM) or the BRAF inhibitor vemurafenib (1 μM) for 72 h led to a reduction in cell counts to 37% ± 6% and 47% ± 4% of controls, respectively (p < 0.001)." (PMID 28811486, 2017). "Here we propose a computational approach utilizing existing high-throughput drug screen data to help identify other combinations that are both synergistic and effective in the context of mutant BRAF melanomas." (PMID 28085880, 2017).
melanoma (continued). "In this manner, the cells are drug-addicted, suggesting that melanoma cells evolve a ‘just right’ level of mitogen-activated protein kinase signaling and the additive effects of MEK and BRAF mutations are counterproductive." (PMID 28263969, 2017). "Metastatic melanoma was treated with chemotherapy in general until recently when the use of BRAF, MEK, CTL-4, and PD-1 inhibitors showed increased survival for patients, even beyond 5 years in a subset of patients." (PMID 28343447, 2017). "The MAPKKK BRAF is a prominent oncogene in melanoma, and inhibitors that target BRAFV600E, the most commonly mutated form, are extremely potent, eliciting high response rates." (PMID 28450382, 2017). "Given the high coexistence rate (29%) of EZH2 gain and BRAF V600E mutation in our cohort, we for the first time evaluated the efficacy of combination therapy with EZH2 and BRAF inhibitors in melanoma cell lines and PDX mouse models." (PMID 29202777, 2017). "One report demonstrated that patients with NRAS mutant metastatic melanoma achieved increased clinical benefit from ipilimumab compared to patients with BRAF/NRAS wild type melanomas." (PMID 29157311, 2017). "In particular, lapatinb works better when combined with other inhibitors of key pathways in melanoma, such as γ-secretase inhibitors, and BRAF inhibitors, highlighting a cooperation among different pathways in melanoma pathogenesis." (PMID 28060735, 2017). "DCA has been tested in multiple cell culture and rodent models of cancer, and PDK1 knock-down has been described to enhance the sensitivity of BRAFV600E positive melanoma to BRAF inhibitors." (PMID 28595656, 2017). "Since both HDAC and BRAF inhibition were able to increase PMCA4b expression in BRAF-mutant melanoma cells, we tested their combined effects." (PMID 28596940, 2017). "BRAF (V600E and V600K) and NRAS (Q61R and Q61L) mutations were detected in 65.9 and 6.8%, respectively, of the primary melanoma tumor biopsies." (PMID 28231855, 2017). "We and others have shown that the knockdown of MCL-1 sensitizes melanoma cells to various treatments, including BRAF or MEK inhibitors and thus, targeting MCL-1 can be a new alternative for melanoma treatment." (PMID 27086916, 2017). "While BRAF and MEK inhibitors improve BRAF mutant melanoma patient outcomes, these inhibitors had limited success in other MAPK dysregulated tumors, with insufficient pathway suppression and likely pathway reactivation." (PMID 28982154, 2017). "We identified 15 patients with V600K-mutant melanoma accounting for 6.9 and 17.2% of the entire and BRAF-mutant population, respectively." (PMID 28797232, 2017). "For example, if testing for melanoma is done using a combination of three single gene tests for BRAF, NRAS, and KIT, this costs less than the panel." (PMID 28196074, 2017). "Taken together, these data strongly supported that loss of BRAF and CRAF in NRAS-mutated murine melanoma cells induced resistances involving a compensatory effect of ARAF." (PMID 28497782, 2017). "Previous studies have demonstrated that the BRAF oncogene protects melanoma cells from anoikis by modulating BAD signaling." (PMID 28753606, 2017). "The present study has demonstrated high efficacy of rMETase in combination with TEM in a BRAF-V600E mutant melanoma PDOX model." (PMID 29156737, 2017). "BRAF inhibitors, now approved for the treatment of patients with melanomas bearing mutant forms of BRAF, are often only effective for a short time before cancer recurs, due to intrinsic and acquired pathway resistance." (PMID 29375561, 2017). "Many of the mechanisms by which BRAF resistance develops involve alternate ‘survival pathways’, through which melanoma cells circumvent the role of BRAF, and thus continue to proliferate." (PMID 29100459, 2017). "LKB1 expression level inversely correlated with MMP-2 expression level in melanoma tissues in the presence of BRAF V600E." (PMID 29371951, 2017).
melanoma (continued). "Since a big proportion of melanomas feature constitutively active MAPK pathway due to mutations in the gene encoding the serine/threonine-protein kinase, BRAF, several groups have investigated the effect of CSPG4 in BRAF mutant melanoma in vitro." (PMID 29375561, 2017). "Exposure of BRAF‐mutant melanoma cells to MAPK inhibitors initially induces up‐regulation of JNK/c‐Jun signaling, a known regulator of EMT‐related genes and of cell adhesion and ECM molecules." (PMID 28069687, 2017). "In melanoma, it has been shown in preclinical models that the combination of lapatinib with the BRAF inhibitor PLX4720 reduces tumor burden and extends latency of tumor regrowth in vivo versus PLX4720 alone." (PMID 28060735, 2017). "In the present analysis, NRAS-mutant cells activated the AXL program and BRAF/NRAS wild type cells the MITF program which also resembles the melanoma pigmentation subtype described earlier." (PMID 27903987, 2017). "Dacarbazine is usually the first line of treatment for melanoma patients until their BRAF status is known." (PMID 29290903, 2017). "Most melanomas harbor alterations in the BRAF, NF1, RAS, MDM2 (KIT) genes, which result in activation of the MAPK and RAS pathways conferring survival advantage by reprogramming crucial cell cycle and apoptotic cellular functions." (PMID 28445515, 2017). "Trametinib is a MEK inhibitor with anti-cancer activity, as an FDA approved cancer drug used for the treatment of BRAF mutant melanoma." (PMID 27965461, 2017). "Unfortunately, limited treatment options are available for the remaining 50% of the melanoma patients whose tumors are wild-type for BRAF (WT BRAF), with a median overall survival of less than one year." (PMID 29290954, 2017). "Whilst our data demonstrate the potential of PAI and MRI in detecting melanoma cell re-differentiation post Hsp90 and BRAF inhibition, each modality has its own merits and demerits for clinical use." (PMID 28811486, 2017). "Vemurafenib in combination with anti-PD-L1 agent atezolizumab (Atezo) was tested in the treatment of naive BRAF mutant melanoma cases, which yielded promising early results in RRs." (PMID 28848761, 2017). "The efficacy of BRAF inhibitor therapies in mucosal melanomas will need to be further assessed in larger studies." (PMID 28380455, 2017). "Combination with BRAF and EZH2 inhibition showed better inhibitory efficacy compared with vemurafenib monotherapy in vitro and in vivo, especially in melanoma containing concurrently BRAF V600E mutation and EZH2 gain." (PMID 29202777, 2017). "An emerging body of data implicates the tyrosine kinase MET in mediating resistance to BRAF inhibitors in BRAFV600E mutant melanoma." (PMID 28147313, 2017). "We treated two BRAF-mutant and one BRAF wild-type melanoma cell lines with the mutant BRAF inhibitor vemurafenib (0.5 μM) and with the HDACis SAHA (1 μM) and valproate (2 mM) alone, or in combination for 48 h." (PMID 28596940, 2017). "Nivolumab confers significant improvement to overall survival when compared with dacarbazine in previously untreated non-BRAF-mutant melanoma patients." (PMID 29179523, 2017). "We use as an experimental approach the inherent heterogeneous response of the sensitive A375 BRAFV600 melanoma cell line to suboptimal BRAF inhibition." (PMID 28573821, 2017). "BRAF inhibitors such as vemurafenib or dabrafenib were approved by FDA and EMA to treat advanced melanoma patients with V600BRAF mutations." (PMID 29299138, 2017). "In this study, we set out to investigate the feasibility of using two imaging approaches in monitoring the downstream cellular consequences of treatment with BRAF and Hsp90 inhibitors in BRAF mutant human melanoma cells." (PMID 28811486, 2017). "Here we show that BAG3 down-modulation interferes with BRAF levels in melanoma cells and sensitizes them to Vemurafenib treatment." (PMID 29113311, 2017).
melanoma (continued). "Unexpectedly, we found that LKB1 inactivation synergism with BRAF V600E significantly promotes melanoma cells invasion and migration by expression of MMP-2." (PMID 29371951, 2017). "Previous studies have also shown that biguanides such as metformin and phenformin, electron transport chain complex I inhibitors, when combined with BRAF inhibitors induce tumor regression in BRAFV600E/PTENfl/fl mouse model of melanoma." (PMID 28753606, 2017). "Here, we show that the EPE peptide not only reduces the growth of many BRAF mutant melanomas, but also several NRAS and NF1 mutant melanomas, insensitive to BRAF inhibition." (PMID 29180761, 2017). "This previous study was focused on BRAF mutations, and similar M%BRAF heterogeneity was demonstrated in melanomas, with 19% of cases having an increased M%BRAF." (PMID 28668077, 2017). "RAC1 mutations are present in all melanoma subtypes, which can be explained by its position at the crossroads of KIT/NRAS/BRAF/MAPK signaling and the PI3K/PTEN/AKT axis." (PMID 28265786, 2017). "Lung carcinoma cell line (A549) and melanoma cell line (A375) were chosen, because they have high incidence of KRAS and BRAF mutations, respectively." (PMID 28262827, 2017). "Impressive clinical results have shown that targeted therapies for melanoma, that is, BRAF and MEK inhibitors, can efficiently treat highly mutagenic solid malignancies by blocking critical cell survival pathways." (PMID 28573821, 2017). "Reactivation of ERK is a major mechanism of acquired resistance of melanoma cells to BRAF inhibitors." (PMID 29050218, 2017). "Several malignant tumours have recently achieved personalized cancer treatment in clinical practice, such as anti-HER2 antibody for HER2-positive breast cancer, anti-EGFR therapy for KRAS wild-type colon cancer, and BRAF inhibitor for BRAF mutant melanoma." (PMID 28548943, 2017). "Our initial studies demonstrated that RhoJ deletion slows the initiation and progression of BRAF mutant melanoma tumors in vivo." (PMID 28753606, 2017). "In the majority of irresectable stage IIIc or metastatic BRAFV600 positive melanoma patients treated with combined BRAF/MEK inhibitors, metabolic alterations occur rapid after the initiation of therapy." (PMID 28915798, 2017). "Encouragingly, a phase I clinical trial evaluating sequential therapy with an anti-PD-L1 antibody, durvalumab, following MEK inhibitor treatment has reported evidence of activity in BRAF WT melanoma patients." (PMID 28807001, 2017). "NRAS mutation was detected in 48 melanomas, corresponding to 18% (48/267) of all melanomas and 33.8% (48/142) of BRAF V600 wild type cases." (PMID 28668077, 2017). "In a multicenter phase II trial, 172 patients with BRAF mutant melanoma with at least one asymptomatic brain metastasis were treated with dabrafenib." (PMID 28993799, 2017). "For melanoma patients, ctDNA monitoring of seven patients with progressive disease after a prior response to anti-BRAF treatments allowed the identification of secondary resistance mutations of the NRAS gene for three of them." (PMID 28484715, 2017). "The traditional targeted therapies for melanoma include BRAF inhibitors (vemurafenib and dabrafenib), MEK inhibitors (trametinib and cobimetinib), tyrosine kinase inhibitors (imatinib) and angiogenesis inhibitors (aflibercept and bevacizumab)." (PMID 28567163, 2017). "Resistance to BRAF inhibition has been reported to be reversible following a period of treatment interruption in melanoma therefore Patient #1 was restarted on single agent vemurafenib." (PMID 28094001, 2017). "We reveal that MITF driven communications between melanoma phenotype subpopulations establishes a paracrine protection to BRAF inhibitor therapy, allowing different phenotypes to prevail." (PMID 28606996, 2017).
melanoma (continued). "The merits of combination therapies were also supported by findings from the coBRIM study, that compared vemurafenib combined with the MEK inhibitor cobimetinib vs. vemurafenib alone in previously untreated unresectable BRAF-mutant melanoma." (PMID 29100459, 2017). "For the melanoma subtypes NM and LMM, BRAF mutation probability decreased with age, although this decrease was weaker if samples were from UV-exposed areas." (PMID 29176861, 2017). "In melanoma cells harboring the BRAFV600E mutation, RARβ activation antagonized the effect of the BRAF inhibitor PLX4032 (vemurafenib)." (PMID 29137417, 2017). "The co-existence of TERT promoter mutations with BRAF or NRAS mutations (in 55% of cases) is associated with poor disease-free and melanoma-specific survival." (PMID 29108273, 2017). "Combined inhibition of BRAF and MEK1/2 (CIBM) improves therapeutic efficacy of BRAF-mutant melanoma." (PMID 28387310, 2017). "The MEK inhibitors currently in use clinically target both MEK1 and MEK2 and when combined with BRAF inhibitors in patients with BRAFV600E‐mutant melanoma prolong progression free survival by an average of 4 months in metastatic disease." (PMID 28097822, 2017). "The mutational status of BRAF (exon 15) and NRAS (exon 2 and 3) was determined in melanoma samples of 217 patients with pyrosequencing and Sanger sequencing." (PMID 28797232, 2017). "We monitored the expression of NRF-1 in melanoma cells in response to treatment with BRAF and MEK inhibitors." (PMID 29050218, 2017). "We retrospectively analyzed melanoma tumors for LKB1 and MMP-2 using immunohistochemistry from 90 melanoma patients, including 27 BRAF V600E patients and 63 BRAF wild type patients, and correlated LKB1 expression with tumor clinicopathological parameters." (PMID 29371951, 2017). "We found that before treatment only SERCA2 was present in the melanoma cell lines and its protein level moderately decreased in response to HDACis in the BRAF-mutant cells." (PMID 28596940, 2017). "Sphere-forming assays demonstrated that KO of BIM also significantly protected the cells against the combination-induced disruption of spheres (P<0.05 or less) in both BRAF and NRAS mutated melanoma cell lines." (PMID 27086916, 2017). "In melanoma, guidance from NICE permits vemurafenib use for BRAF V600 mutated tumours, meaning one patient with a V600R mutation received the drug and others with V600G/M and V600K mutations were eligible." (PMID 28196074, 2017). "This pathway analysis is remarkably similar to what has been found in human melanomas that have become resistant to BRAF inhibitors." (PMID 28173755, 2017). "Further, MO5, a mouse melanoma cell line with WT BRAF too responded to AZD1775, showing tumor regression." (PMID 29290954, 2017). "To show the functionality of CVE, we applied it in a single colorectal cancer patient (as a ’molecular tumour board’ example), as well as in a cohort study of 93 BRAF-wt/RAS-wt melanomas, where druggable targets are poorly understood." (PMID 28545463, 2017). "Specifically, hepatocyte growth factor (HGF), the cognate ligand for the RTK MET, has been shown to convey resistance to vemurafenib and a related analog, PLX4720, in BRAF mutant melanoma cell lines." (PMID 28147313, 2017). "To identify a representative cell line, we assessed the AXL and MITF expression status in a panel of melanoma cell lines and their link to response to BRAF inhibition." (PMID 28606996, 2017). "Consistent with our TMFS and kinase assays, MBZ is toxic to patient-derived melanoma cells harboring either WT or mutant BRAF in the presence of trametinib." (PMID 28157711, 2017).